BECN1 (beclin 1)
Diseases named in the same sentence as BECN1 in open-access papers (continued):
Sharing a sentence is not in itself a finding about the gene and the disease.
memory impairment (4 papers, 2020 to 2023). "Systemic TAT‐Beclin 1 injections, at a dose which stimulates autophagy, effectively rescued memory impairment, in line with the previous report." (PMID 32729663, 2020). "Although we have shown that Beclin 1 and PTEN are both the endogenous ubiquitination targets of Nedd4 in the hippocampus, our results do not exclude the possibility that Beclin 1 and PTEN are also the ubiquitination targets of other Nedd family proteins involved in Ndfip1-mediated memory impairment." (PMID 37023120, 2023). "Although we have shown that spatial training decreased endogenous Beclin 1 and PTEN ubiquitination in the hippocampus, it is not known whether Beclin 1 and PTEN are downstream effectors of Ndfip1 in Ndfip1-mediated memory impairment." (PMID 37023120, 2023).
sarcoma (4 papers, 2016 to 2021). A usually aggressive malignant neoplasm of the soft tissue or bone. "The reduced sarcoma growth in the CTX + MAA group was accompanied by enhancement of Bax/Bcl-2/Caspase 3 mediated apoptosis, and inhibition of Beclin-1/LC-3 II mediated autophagy." (PMID 27043621, 2016).
scrapie (4 papers, 2018 to 2021). A fatal disease of the nervous system in sheep and goats, characterized by pruritus, debility, and locomotor incoordination. "Downregulation of these positive autophagy gene regulators (Becn1, Fbxw7, Gas5 and Atg5) has been described in the CNS of scrapie-infected mice (both wild-type or transgenic) and naturally scrapie infected sheep." (PMID 34283400, 2021). "BECN1 expression levels also correlated negatively (ρ = −0.833, P < 0.05) with PrPSc deposition in this tissue in scrapie sheep." (PMID 30760781, 2019). "We carried out a first gene expression analysis of ATG5, BECN1, ATG9 and LC3-B in naturally scrapie-infected sheep brains." (PMID 30760781, 2019). "Here, transcript expression levels of genes ATG5 and ATG9 decreased significantly in thalamus and cerebellum, respectively, of scrapie-infected sheep, and BECN1 expression displayed a negative correlation with prion deposition in scrapie thalamus." (PMID 30760781, 2019).
small cell lung carcinoma (4 papers, 2015 to 2024). Small cell lung cancer (SCLC) is a highly aggressive malignant neoplasm, accounting for 10-15% of lung cancer cases, characterized byrapid growth, and early metastasis. "It is reported that miR-30 or its homology miR-30a, miR-30a-5p binds to Beclin-1 mRNA to block autophagy-induced chemoresistance in chronic myeloid leukemia, gastric cancer, osteosarcoma, small cell lung cancer (SCLC) and other variety of cancers." (PMID 35211417, 2022).
tongue squamous cell carcinoma (4 papers, 2019 to 2023). A squamous cell carcinoma that arises from the tongue. "In tongue squamous cell carcinoma, overexpression of BECN1 inhibited cell migration, while knockdown of BECN1 promoted migration." (PMID 31272261, 2019). "Wang’s group have also shown that reduced BECN1 results in decreased ATG4, ATG5 and LC3-II levels, as well as intensified proliferation, migration and invasion of tongue SCC cells." (PMID 33297472, 2020). "Additionally, overexpression of Beclin-1 increased the levels of ATG4, ATG5, and LC3-II proteins in tongue squamous cell carcinoma cell lines." (PMID 38028434, 2023).
vascular dementia (4 papers, 2022 to 2025). A degenerative vascular disorder affecting the brain. "Another research group demonstrated that açaí pulp increased the mRNA expression of protein that in humans is encoded by the BECN1 gene (Beclin-1) and reduced LC3B and p62 in the hippocampus of rats subjected to the vascular dementia model." (PMID 40648018, 2025). "The number of LC3II and Beclin-1 positive cells in the hippocampus of the vascular dementia rats increased significantly, and the staining of the positive cells was darker." (PMID 36767264, 2023). "The results of the Western blot also showed that the expression of the autophagy-related proteins LC3II and Beclin-1 in the hippocampus of vascular dementia rats were significantly increased, and the expression decreased after exercise intervention." (PMID 36767264, 2023). "The LC3II and Beclin-1 proteins, detected by immunohistochemistry and a Western blot analysis, showed that the protein expression in the hippocampi of rats with vascular dementia increased." (PMID 36767264, 2023). "We confirmed that the expression of Bcl-2 was down-regulated in the hippocampus of vascular dementia rats, while LC3II and Beclin-1 were significantly increased." (PMID 36767264, 2023).
allergic asthma (3 papers, 2022 to 2025). A asthma with a basis in a pathological type I hypersensitivity reaction. "In the OVA-induced allergic asthma mouse model, the expressions of ATG5, LC3, and Beclin 1 in the lungs and lavage fluid decreased." (PMID 36330226, 2022).
anaplastic astrocytoma (3 papers, 2023 to 2025). "Furanocoumarin only increased the level of Beclin 1 in anaplastic astrocytoma." (PMID 38255833, 2024).
aneurysm (3 papers, 2019 to 2023). Bulging or ballooning in an area of an artery secondary to arterial wall weakening. "On the other hand, mRNA expression of LC3, ATG5, Beclin-1, and ATG7 tended to increase in aneurysm samples, although in a nonsignificant manner." (PMID 34754985, 2021).
astrocytic tumor (3 papers, 2019 to 2022). A glial tumor of the brain or spinal cord showing astrocytic differentiation. "Loss of Beclin-1 has been reported to promote the progression of astrocytic tumors which explains our observation that Beclin-1 expression levels were low." (PMID 36612214, 2022). "Next, we utilized lentivirus to establish stable BECN1-knockdown RD cells and U251 (human astroglioma) cells, then we infected stable RD and U251 cells with EV71 and checked replication efficiency at different time points in two different cells." (PMID 32674313, 2020).
bladder tumor (3 papers, 2019 to 2024).
brain cancer (3 papers, 2014 to 2020). A primary or metastatic malignant neoplasm affecting the brain. "The prognostic significance of Beclin-1 has been studied in several types of solid tumors, and decreased expression of Beclin-1 was correlated with tumor progression in breast, ovarian and brain cancers." (PMID 24885292, 2014). "Abnormal expression of Beclin-1 has been found in human melanoma, colon, ovarian and brain cancers." (PMID 24885292, 2014). "Furthermore, our Western blot analysis showed an up-regulation of LC3B, which is a marker for the formation of autophagic vesicles, Beclin-1 and ATG5 in U-87 MG, U-251 MG, and Daoy brain cancer cells." (PMID 32971907, 2020).
brain trauma (3 papers, 2009 to 2025). "Since the autophagy process is proven to be active in the TBI process, the present study investigates the use of LC3B, Beclin 1, p62, and LAMP2A as a forensic diagnostic marker for brain trauma." (PMID 40356869, 2025). "A number of studies have reported that a cellular biomarker for autophagy, Beclin 1, is upregulated in ischemic brain injuries." (PMID 37509524, 2023).
colorectal adenocarcinoma (3 papers, 2010 to 2016). The most common type of colorectal carcinoma. "The immunohistochemical patterns of Beclin 1 expression and their prognostic relevance were studied in formalin-fixed tissues from 155 patients with colorectal adenocarcinoma treated with surgery alone." (PMID 20842118, 2010). "In the present study, we evaluated the expression of autophagy-related proteins (ATG5, BECN1, and LC3) in primary colorectal adenocarcinomas and their relationship with clinicopathological parameters and clinical outcomes." (PMID 24723943, 2014).
coronary artery disease (3 papers, 2012 to 2022). "A negative correlation between beclin-1 and DPP4 activity was observed in patients with coronary heart disease." (PMID 32340263, 2020).
cyst (3 papers, 2017 to 2025). A sac-like closed membranous structure that may be empty or contain fluid or amorphous material. "In the ADPKD zebrafish model, atg5-KO inhibits autophagy to promote cyst formation, whereas the use of BECN1 peptide can activate autophagy to improve cyst formation." (PMID 40851276, 2025).
epithelial ovarian tumor (3 papers, 2013 to 2023). "In summary, in this study, we describe the expression status of Beclin 1 in normal human ovary, benign, borderline and malignant epithelial ovarian tumor tissues." (PMID 23573264, 2013). "In the present study, the methods of Western blotting and immunohistochemistry (IHC) were utilized to investigate the expression status of Beclin 1 and Bcl-xL in fresh ovarian tissues and paraffin-embedded epithelial ovarian tumor tissues." (PMID 23573264, 2013). "In the present study, we measured the expression levels of Beclin 1 and Bcl-xL by Western blotting and immunohistochemistry (IHC) in human epithelial ovarian tumors with normal ovarian tissues as controls." (PMID 23573264, 2013). "Furthermore, we found that decreased expression of Beclin 1 was correlated with the development of epithelial ovarian tumors." (PMID 23573264, 2013). "In the present study, we investigated the expression patterns of Beclin 1 and Bcl-xL, by Western blotting and IHC, using fresh ovarian tissues and a TMA containing a series of benign, borderline and malignant epithelial ovarian tumors." (PMID 23573264, 2013).
hypopharyngeal carcinoma (3 papers, 2015 to 2021). Carcinoma, predominantly squamous cell, arising from the epithelial cells of the hypopharynx. "This was confirmed by increased Beclin-1 and LC3B protein levels in hypopharyngeal cancer cells treated with metformin." (PMID 33652909, 2021).
laryngeal carcinoma (3 papers, 2015 to 2025). Carcinoma that arises from the laryngeal epithelium. "This is suggestive of possible regulation by NSD1 of not only ULK1 at the transcriptional level but also of its downstream target Beclin-1 in laryngeal cancer cell types." (PMID 38346948, 2024).
lipid metabolism disorders (3 papers, 2017 to 2024). "BBM mitigates liver lipid metabolism disorders by modulating the SIRT1/LKB1/AMPK pathway, regulating the expression of autophagy markers LC3a/b, Beclin 1, and p62, and inducing autophagy to decelerate the progression of NAFLD." (PMID 39175576, 2024).
liver cirrhosis (3 papers, 2013 to 2021). "Remarkable heterogeneity was observed in the meta-analysis of the correlation between Beclin-1 expression and liver cirrhosis or HBsAg." (PMID 30107804, 2018). "Significant heterogeneity existed in the analysis of the correlation of Beclin-1 expression and liver cirrhosis or HBsAg." (PMID 30107804, 2018). "Considerable interstudy heterogeneity was observed in the analyses of the correlation between Beclin-1 expression and liver cirrhosis (P = 0.02, I2 = 57%) or HBsAg (P = 0.08, I2 = 47%)." (PMID 30107804, 2018). "Beclin-1 was irrelevant to liver cirrhosis of HCC patients from both Asia (OR = 1.27, 95% CI = 0.72–2.25, P = 0.42) and Egypt (OR = 10.03, 95% CI = 0.74–136.23, P = 0.08)." (PMID 30107804, 2018). "Subgroup analysis based on geographic region showed that Beclin-1 expression was irrelevant to liver cirrhosis of HCC patients from both Asia and Egypt." (PMID 30107804, 2018). "This suggested that regional difference did not influence the association between Beclin-1 expression and liver cirrhosis in this study." (PMID 30107804, 2018). "Here, we detected Beclin 1 expression level in the subtypes of ICC and ECC, and in other pathophysiological contexts, such as HBV infection, liver cirrhosis and cholecystolithiasis." (PMID 24303007, 2013). "Considering the eventual molecular print of Beclin-1 negative expression in HCC occurrence, a close monitoring of this altered gene in cases of liver cirrhosis might be of significance in HCC early detection." (PMID 33906303, 2021). "However, we did not detect any correlations between Beclin 1 and other clinicopathological features, including tumor subtypes, vascular invasion, HBV infection, liver cirrhosis, cholecystolithiasis and TNM stage." (PMID 24303007, 2013).
metastatic melanoma (3 papers, 2020 to 2022). A melanoma that has spread from its primary site to another anatomic site. "For instance, Hara and Nakamura (2012) reported that autophagy activity is elevated in metastatic melanoma, as evidenced by Beclin-1 overexpression." (PMID 35370701, 2022). "Moreover, Beclin-1 and LC3 have been found to be overexpressed in advanced or metastatic melanoma as compared to early primary lesions, and have also been linked to cell proliferation markers like Ki67 expression." (PMID 35370701, 2022). "In addition to our previous study where we demonstrated decreased expression of Beclin-1 in metastatic melanomas, we show here that the expression of two more ATG proteins, ATG5 and ATG7, are reduced in primary and metastatic melanomas compared to benign nevi." (PMID 34458153, 2021).
myocarditis (3 papers, 2018 to 2021). Myocarditis is a condition that is characterized by inflammation of the heart muscle (myocardium). "To evaluate the relevance of autophagy in fibrotic heart disorders, we analyzed expression of autophagy-related proteins LC3B, Beclin-1 and ATG5 in endomyocardial biopsies obtained from iDCM patients who developed fibrotic phenotype in comparison to patients with healed myocarditis (no fibrosis)." (PMID 33668422, 2021).
nasal polyps (3 papers, 2021 to 2024). "By contrast, nasal application of CQ significantly decreased Beclin‐1 protein expression in nasal polyps." (PMID 38888464, 2024). "IHC revealed significantly increased Beclin‐1 protein expression in nasal polyps after both systemic and intranasal application of rapamycin, LY294002, and AS605240 compared with the control." (PMID 38888464, 2024). "WB revealed significantly increased Beclin‐1 protein expression in nasal polyps after systemic application of rapamycin, LY294002, and AS605240 compared with the control." (PMID 38888464, 2024). "Meanwhile, intranasal application of rapamycin significantly increased Beclin‐1 protein expression in nasal polyps compared with the control." (PMID 38888464, 2024). "By contrast, systemic application of CQ and 3‐MA significantly reduced Beclin‐1 protein expression in nasal polyps." (PMID 38888464, 2024). "The expression of Beclin 1 decreased, whereas p62 mRNA and protein levels increased in nasal polyps, compared with normal inferior turbinate mucosa." (PMID 35747690, 2022). "Western blot analysis showed that the levels of Beclin 1 protein in nasal polyps were downregulated in patients with eCRSwNP (P < 0.001) or noeCRSwNP (P < 0.001), compared with control tissues." (PMID 35747690, 2022). "In addition, intranasal application of CQ significantly decreased Beclin‐1 protein expression in nasal polyps." (PMID 38888464, 2024). "The levels of LC3II, Beclin 1, and hypoxia-inducible factor-1α are elevated in nasal polyps." (PMID 35747690, 2022). "Beclin 1, PINK1, BNIP3, and FUNDC1 levels were significantly reduced in the nasal polyps of patients with eCRSwNP or noeCRSwNP." (PMID 35747690, 2022).
nutritional deficiency (3 papers, 2021 to 2024). "Under stress conditions such as hypoxia and nutritional deficiency, Hif-1 regulates AMPK activation, which results in the induction of autophagy via BINP3/Beclin-1 or by mTOR inhibition." (PMID 39201332, 2024).
parasitemia (3 papers, 2019 to 2023). "We observed that mice deficient in autophagy (heterozygous knockout for Beclin-1 gene) developed a more aggressive infection characterized by higher parasitemia values and earlier death than did autophagy-competent mice." (PMID 36004334, 2022). "Acute T. cruzi infection in the autophagy deficient BECN1 heterozygous knock-out mice (Becn1+/-), generated in the C57BL6/J background in the Beth Levine laboratory, was associated with higher parasitemia, cardiac parasitism and earlier death compared to their WT counterpart." (PMID 37064813, 2023). "Interestingly, the curve of parasitemia of WT animals can be divided in three periods; at early times after infection (5 and 7 dpi) has a high slope and reaches higher values, statistically significant, than Beclin-1 KD mice or WT animals treated with the autophagic inhibitors, CQ and DFMO." (PMID 30829115, 2019). "At these conditions, Beclin-1 wild type mice (Bcln+/+) developed high parasitemia values and lost weight significantly compared with non-infected mice." (PMID 30829115, 2019).
promyelocytic leukemia (3 papers, 2021 to 2024). "Beclin-1’s influence extends beyond autophagy regulation, impacting therapeutic outcomes and drug resistance mechanisms in acute promyelocytic leukemia (APL) and chronic myeloid leukemia (CML)." (PMID 38887520, 2024). "Additionally, the enhancement in the rate of autophagic cell death in human HL-60 promyelocytic leukemia cells, as well as in the expressions of LC3-II and Beclin-1, was reported in a dose-dependent manner." (PMID 36670976, 2023).
rheumatoid arthritis (3 papers, 2016 to 2020). A chronic, systemic autoimmune disorder characterized by inflammation in the synovial membranes and articular surfaces. "It was reported that autophagosome formation, Beclin‐1 expression, and LC3‐II conversion increase in rheumatoid arthritis synovial fibroblasts following thapsigargin treatment." (PMID 32592208, 2020). "A recent study observed a significant increase of Beclin 1 and LC3-II along with a remarkable decrease of p62 in both IL-1β-stimulated rheumatoid arthritis fibroblast-like synoviocytes and RSC-364 cells after APS treatment, suggesting APS induces autophagy in rheumatoid arthritis." (PMID 30999666, 2019).
skin melanoma (3 papers, 2013 to 2025). "Nevertheless, our finding of a strict correlation between Beclin-1 expression and the clinical outcome of UM support the idea that alteration in autophagy may be a particularly attracting targetable way to treat UM progression, as it has been proposed for skin melanoma." (PMID 33330070, 2020).
Spinocerebellar ataxia type 3 (3 papers, 2012 to 2025). "Deficiency in beclin-1 has been observed in post-mortem AD brains and spinocerebellar ataxia type 3 (SCA3) patients' fibroblasts." (PMID 23300858, 2012). "PolyQ tracts in ataxin 3, a deubiquitinase associated with spinocerebellar ataxia type 3 (SCA3), interact with beclin 1, a key initiator of autophagy." (PMID 36940239, 2023).
synucleinopathies (3 papers, 2019 to 2021). "In rodent α-synucleinopathy models, promoting autophagy by expressing BECN1, ATG7, LAMP2A or treatment with rapamycin reduces α-synuclein levels and ameliorates pathological disease markers." (PMID 33556113, 2021).
testicular cancer (3 papers, 2022 to 2024). A primary or metastatic malignant neoplasm that affects the testis. "In a panel of human cell lines derived from breast, colorectal, head and neck, and testicular cancers, we demonstrated that PV-10 induces cytotoxicity by apoptotic and autophagic pathways involving caspase-mediated PARP cleavage, downregulation of SQSTM1/p62, and upregulation of beclin-1." (PMID 38672602, 2024).
type 1 diabetes (3 papers, 2020 to 2024). "The heart damage caused by type I diabetes was weakened in Beclin 1‐deficient mice." (PMID 38113341, 2024). "The overexpression of Beclin 1 led to increased damage, indicating the role of autophagy in the hearts of mice with type I diabetes." (PMID 38113341, 2024). "The current study confirmed the impaired autophagy function in STZ-induced type-1 diabetes, and myocardial I/R excessively induced autophagy status indicated by increased ratio of LC3II/LC3I and Beclin-1 expression with decreased p62." (PMID 32337288, 2020).